EIF4A3 (eukaryotic translation initiation factor 4A3)
Diseases named in the same sentence as EIF4A3 in open-access papers (continued):
Sharing a sentence is not in itself a finding about the gene and the disease.
tumor (continued). "In the present study, both circ-231 and eIF4A3 were overexpressed in ESCC and participated in TPI1 and PRDX6 mRNA initial translation, suggesting that both circ-231 and eIF4A3 were involved in tumor progression via post-transcriptionally regulating the expression of TPI1 and PRDX6." (PMID 38577609, 2024). "Meanwhile, our analysis of the correlation between EIF4A3 and immune checkpoint genes indicates that EIF4A3 may play a pivotal role in the regulation of tumor immunity within complex molecular pathways." (PMID 37777564, 2023). "Moreover, the increased EIF4A3 expression in TAMs educated tumor cells promoted the biosynthesis of cSERPINE2." (PMID 36797769, 2023). "As such, by elucidating the precise role of EIF4A3 in tumor development, it may enable more personalized and precise immunotherapy in the future." (PMID 37777564, 2023). "Additionally, different tumor types have varying levels of response to EIF4A3’s effects on tumor immunity." (PMID 37777564, 2023). "Hence, circ_0020256 drove transplanted tumor growth in the nude mice by modulating EIF4A3/KLF4 pathway." (PMID 37179359, 2023). "In conclusion, our findings reveal that EIF4A3 is strongly correlated with tumor immunity across varying types of human cancers and may serve as a novel predictor of immunotherapy response." (PMID 37777564, 2023). "Additionally, TAM-derived IL-6 in turn elevated CCL2 and EIF4A3 expression in tumor cells by increasing the activation of the JAK2-STAT3 pathway." (PMID 36797769, 2023). "Given the diverse nature of the relationship between immune cells and EIF4A3 expression in human cancers, we hypothesize that there is a complex correlation between the antitumor or pro-tumor response of immune cells and EIF4A3 expression." (PMID 37777564, 2023). "In conclusion, these findings provide robust evidence that the novel circular RNA circ_0009092, which could be regulated by EIF4A3, acts as a tumor suppressor in CRC progression." (PMID 38008713, 2023). "In summary, high expression of EIF4A3 may contribute to tumor progression by remodeling the immune microenvironment in BLCA patients; however, owing to its association with PD-L1 expression, it may serve as a predictor for immunotherapy response." (PMID 37180585, 2023). "In addition, increased expression of EIF4A3 was found in The Cancer Genome Atlas (TCGA) and Clinical Proteomic Tumor Analysis Consortium (CPTAC) HCC samples when compared with normal samples." (PMID 36932387, 2023). "In transformed cells and cancer cells, the expression levels of many translation initiation factors, including eIF4A3, are altered, indicating that eIF4A3 may be involved in carcinogenesis and tumor progression, which is a potential therapeutic target." (PMID 35546509, 2022). "Indeed, in the TCGA cohort, HCC samples with high EIF4A3 levels were enriched in key tumour‐related pathways, such as tRNA processing, nucleotide excision repair, cell cycle mitotic and DNA repair." (PMID 36419260, 2022). "Interestingly, the high EIF4A3 group was enriched in tumour‐related pathways such as tRNA processing, nucleotide excision repair, cell cycle and DNA repair." (PMID 36419260, 2022). "Studies have proved that eIF4A3 regulates tumor cell function and drug resistance by regulating the TNF-α/NF-kB signaling pathway, whether this signaling pathway was involved ineIF4A3-regulated GC carcinogenesis needs further investigation." (PMID 35873631, 2022). "In vitro EIF4A3‐silencing (or pharmacological inhibition) resulted in reduced aggressiveness, and hindered xenograft‐tumours growth in vivo, whereas EIF4A3 overexpression increased tumour aggressiveness." (PMID 36419260, 2022). "LncRNAs may modulate tumor gene expression by affecting the recruitment of EIF4A3 to RNA, EJC assembly, RNA splicing, and other downstream events." (PMID 34458150, 2021). "Recent research has also shown that EIF4A3 may have potential value in tumor diagnosis, treatment, and prognosis." (PMID 34458150, 2021).
tumor (continued). "IF was performed to confirm the change in the subcellular localization of EIF4A3 protein in xenograft tumor, and the results showed that the expression of EIF4A3 protein from the circ_0004296 overexpression group was increased in the nucleus as compared to that in the control group." (PMID 34696782, 2021). "Genes positively correlated with EIF4A3 were tumor-related genes." (PMID 34458150, 2021). "In summary, circPRKAR1B may crucially affect tumour proliferation and lung metastasis in OS through EIF4A3-induced circPRKAR1B/miR-361-3p/FZD4 axis." (PMID 34716310, 2021). "Therefore, we conclude that EIF4A3 may serve as a powerful biomarker for tumor screening, prognosis, and individualized gene strategies in a broad range of malignancies." (PMID 37777564, 2023). "Additionally, higher EIF4A3 protein levels were observed in HCC samples from the CPTAC cohort compared to NTAT, associated with lower survival and higher recurrence, and correlated with the number of tumours, alpha‐fetoprotein levels and tumour size." (PMID 36419260, 2022). "However, EIF4A3 levels were correlated with the expression of key oncogenic splicing variants in HCC samples from the retrospective cohorts, and with important clinical features such as tumour differentiation and diameter." (PMID 36419260, 2022). "In addition, EIF4A3 could serve as a negative regulator of circRNA_100290 and a tumour suppressor in GC." (PMID 34182990, 2021). "An unexpected finding is that pharmacological inhibition of EIF4A3 results in the abolishment of stress granules, uncovering a previously unknown role of EIF4A3 in this type of RNA metabolism and underscoring its importance in stress regulation and tumour biology." (PMID 31069274, 2019). "LINC01016 blocks the binding of EIF4A3 to MMP9 mRNA, thereby inhibiting EIF4A3-mediated NMD, leading to increased MMP9 mRNA and protein expression, and promoting tumor progression." (PMID 39881131, 2025). "To further investigate the effects of EIF4A3 on cell proliferation in vivo, we constructed a xenograft tumor model using stable sh-NC-MCF-7 and sh-EIF4A3-MCF-7 cells." (PMID 40092703, 2025). "When LINC01016 is overexpressed, the binding of EIF4A3 and MMP9 mRNA is blocked, and NMD is inhibited, leading to the upregulation of MMP9, thus promoting tumor progression." (PMID 39881131, 2025). "Circ_RPPH1 promotes tumor growth and EMT in BUC by inhibiting EIF4A3-mediated mRNA regulation, activating the EIF4A3/N-cadherin/Vimentin pathway." (PMID 40346652, 2025). "The increased IL‐6, in turn, elevates EIF4A3 and CCL2 levels within tumor cells, which upregulate circSERPINE2 biogenesis in tumor cells and promote the recruitment of TAMs in a positive feedback mechanism." (PMID 39901896, 2025). "Functional assays underscored the oncogenic potential of EIF4A3, characterized by its ability to promote ICC cell proliferation, migration, invasion, and tumor stemness, coupled with concomitant suppression of apoptosis." (PMID 39836545, 2025). "The eukaryotic translation initiation factor 4A3 (EIF4A3), a crucial component of the exon junction complex, plays a pivotal role in tumor regulation." (PMID 39030638, 2024). "Studies have shown that circRNAs can bind to RBPs, such as Quaking (QKI), HuR (ELAVL1), eukaryotic translation initiation factor 4A3 (EIF4A3), and AlkB homolog H5 (ALKBH5), to play important roles in tumor progression." (PMID 37296107, 2023). "Simultaneously, the relationship between EIF4A3 expression and immune infiltration, and immune checkpoint gene expression was analyzed using the TIMER2 (Tumor Immune Estimation Resource version 2.0) tool." (PMID 37180585, 2023). "More importantly, IL-6 in turn increased the EIF4A3 and CCL2 levels within tumor cells in a positive feedback mechanism, further enhancing tumor cSERPINE2 biogenesis and promoting the recruitment of TAMs." (PMID 36797769, 2023).
tumor (continued). "In the occurrence of cancer, EIF4A3 regulates cell cycle and apoptosis via the TNF-α/NF-ĸB signaling pathway and other important signaling pathways, promotes tumor cell migration and invasion, and the formation of drug resistance." (PMID 33149201, 2020). "Concerning the genes related to tumor progression, we found HSP90AB1, GRB2, ERBB2/3, EIF4A3, HDGF, and CSNK2B." (PMID 25625699, 2015). "We determined that LINC01016 can blocks the binding of EIF4A3 to MMP9 mRNA, thereby inhibiting EIF4A3-mediated nonsense-mediated RNA decay (NMD), increasing MMP9 mRNA level and protein expression levels to promote tumor progression." (PMID 39881131, 2025). "Our findings demonstrated that circPVT1 promotes tumor progression through dual mechanisms: cP104aa increases c‐MYC expression by forming a complex with HNRNPK, while circPVT1 enhances c‐MYC expression by binding to the EIF4A3 protein." (PMID 40966379, 2025). "Overall, EIF4A3 and CDC5L are expected to become tumor biomarkers." (PMID 40092703, 2025). "The overexpression of EIF4A3 in different cancers has the potential to drive tumor progression by regulating RNA splicing, translation, and nonsense-mediated decay." (PMID 41189592, 2025). "Notably, IL-6 can elevate the levels of EIF4A3 and CCL2 in tumor cells via activation of the JAK2/STAT3 pathway, further facilitating tumor cSERPINE2 biogenesis and inducing TAMs recruitment." (PMID 38397395, 2024). "HPN-AS acted as a tumor suppressor within HCC through binding and facilitating eIF4A3 degradation." (PMID 39114737, 2024). "Furthermore, IL-6 in turn increased the EIF4A3 and CCL2 levels within tumor cells in a positive feedback mechanism, further enhancing tumor cSERPINE2 biogenesis and promoting the recruitment of TAMs." (PMID 36797769, 2023). "Moreover, IL-6 in turn increased the EIF4A3 and CCL2 level within tumor cells in a positive feedback manner, further enhancing tumor cSERPINE2 biogenesis and promoting the recruitment of TAMs." (PMID 36797769, 2023). "Moreover, recent studies have demonstrated that EIF4A3 could regulate EMT process and facilitate tumor progression in HCC." (PMID 38383334, 2024). "The expression of eIF4A3 in tumor tissues was significantly higher than that in nontumor tissues." (PMID 35677890, 2022). "Therefore, hsa_circ_0136666 could effectively promote tumor cells proliferation in vitro without being detected by immune cells, and the biosynthesis of hsa_circ_0136666 is also regulated by EIF4A3." (PMID 38093288, 2023). "Therefore, eIF4A3 and FUS may constitute key lncRNA-binding proteins that could be part of a pan-cancer molecular mechanism that mediates the tumorigenic properties of most oncogenic lncRNAs and/or generally promotes lncRNA secretion into the systemic circulation from the tumor site." (PMID 35729321, 2022). "For DDAH1, ARGI2, eIF4A3, PRDX3 and Par4 results have not shown significant changes in their respective mRNA levels in tumor compared to benign tissues (Data not shown)." (PMID 21347291, 2011). "Nevertheless, ectopic expression of cSERPINE2 in MCF-7 cells did not regulate the expression of EIF4A3 or CCL2 or activation of the JAK2-STAT3 pathway, which indirectly indicated that cSERPINE2 overexpression did not affect tumor cell proliferative and invasive capacity in vitro." (PMID 36797769, 2023).
cancer (65 papers, 2019 to 2026). A tumor composed of atypical neoplastic, often pleomorphic cells that invade other tissues. "Cancer-derived mutations in these interacting residues were retrieved from cBioPortal and evaluated for their impact on EIF4A3–mRNA binding affinity or structural stability." (PMID 41189592, 2025). "Evaluation or prediction of cancer mutations that reduce or induce eIF4A3’s affinity for mRNA shall contribute to better molecular-level understanding of these systems." (PMID 41189592, 2025). "EIF4A3 plays a crucial role in post-transcriptional regulation and has been reported to interact with RNAs and act as a diagnostic marker in many cancers." (PMID 38383334, 2024). "High expression of eIF4A3 is usually associated with disease progression and poor prognosis in various cancer types, which makes it an appealing candidate for cancer therapy." (PMID 38036629, 2024). "Conversely, lower expression of EIF4A3 was significantly associated with a poorer outcome in two cancers including TCGA-THYM and TCGA-DLBC." (PMID 37777564, 2023). "In our analysis, we also found a significant association between EIF4A3 and nearly all m6A regulators in the majority of human cancers studied." (PMID 37777564, 2023). "Overexpression of eIF4A3 is associated with poor prognosis of patients with various cancers and systematic analysis of co-expression reveals an association between eIF4A3 and known proteins involved in the cell cycle and apoptosis." (PMID 36142288, 2022). "In cancer cells, EIF4A3 is associated with posttranscriptional modification, cell cycle progression, and acceleration of cell growth." (PMID 32973867, 2020). "Notably, high expression levels of EIF4A3 were negatively associated with patient prognosis across various cancer types." (PMID 37777564, 2023). "Abnormal expression or mutations of EIF4A3 have been associated with various types of cancer, suggesting that the increased m6A levels observed in many cancers may be a result of aberrant splicing machinery and incomplete protection of exon junctions by the EJC." (PMID 39416026, 2024). "Regarding markers associated with selenoprotein regulation, we found that both SELENOF and eIF4a3 levels were higher in cancer tissues obtained from African Americans." (PMID 41563517, 2026). "We also plan to further investigate the broader regulatory role of EIF4A3 and its potential combined impact with circPCSK6 in cancer treatment strategies." (PMID 39836545, 2025). "Alterations within the EIF4A3 gene can impair this recruitment, ultimately suppressing NMD, and it has been linked to cancer progression." (PMID 41189592, 2025). "These crucial roles of EIF4A3 make it an important factor within the PTC recognition and degradation processes, and its dysregulation or overexpression has been implicated in cancer progression or tumorigenesis." (PMID 41189592, 2025). "In some cancer cell, EIF4A3 influences the generation of circular RNAs through alternative splicing, promoting the tumorigenesis." (PMID 40641186, 2025). "Generally, EIF4A3 modulates circRNAs to impose pleiotropic effects on cancer cells with functional significance." (PMID 39550559, 2024). "Collectively, our research revealed the anti-cancer functions of HPN-AS1 in HCC through the facilitation of eIF4A3 breakdown." (PMID 39114737, 2024). "Elucidating the detailed mechanism by which eIF4A3 unwinds secondary structure in cancer cells is especially important to identify a potential therapeutic target." (PMID 38577609, 2024). "Conversely, EIF4A3 expression is significantly lower in only 3 cancers, including PCPG, ACC and KICH." (PMID 37777564, 2023). "To investigate the correlation between EIF4A3 and cancers, we analyzed its mRNA expression levels in various tissues using multiple databases." (PMID 37777564, 2023). "Our findings indicate that EIF4A3 expression is generally higher in cancer cell lines compared to normal tissues." (PMID 37777564, 2023).
cancer (continued). "Data from UCSC Xena database was used to explore the expression of EIF4A3 and 24 inhibitory genes and 36 stimulatory genes in 40 human cancers." (PMID 37777564, 2023). "Overall, our analysis of TCGA and GTEx data suggests that EIF4A3 is overexpressed in most cancer types." (PMID 37777564, 2023). "Meanwhile, analysis of publicly available databases revealed that EIF4A3 expression was significantly related to immune score and immune cell levels in most cancer types." (PMID 37777564, 2023). "Despite our comprehensive analysis of the prognostic and immunological roles of EIF4A3 in pan-cancer, we acknowledge that there are still some limitations to our study." (PMID 37777564, 2023). "Recently, EIF4A3 was recognized as a putative oncogene, leading to an increase in the studies determining its role in cancer development." (PMID 37180585, 2023). "We also conducted Kaplan–Meier analysis to verify the impact of EIF4A3 expression on patient prognosis in several cancers." (PMID 37777564, 2023). "Based on the critical role of EIF4A3 in epigenetics, EIF4A3 was found to regulate cancer progression in different types of human cancer." (PMID 37777564, 2023). "We used the BioGPS database to determine the expression level of EIF4A3 in both normal tissues and cancer cell lines." (PMID 37777564, 2023). "We investigated the potential of EIF4A3 in immunotherapy by studying its relationship with immune checkpoint genes in human cancers." (PMID 37777564, 2023). "Our analysis of 44 types of cancer revealed that LUSC, STES, and LUAD had the strongest association between EIF4A3 expression and immune score." (PMID 37777564, 2023). "TCGA database was utilized to obtain EIF4A3 expression patterns in cancers and paraneoplastic tissues." (PMID 37777564, 2023). "The analysis of differentially expressed genes related to EIF4A3 indicates that it is involved in many cancer-related pathways, such as Notch and JAK-STAT3 signal pathway." (PMID 37322413, 2023). "In conclusion, according to our above findings, the overexpression of circMAP2K2 induced by EIF4A3 in GC is related to the mechanism of promoting cancer." (PMID 37752765, 2023). "To investigate the role of EIF4A3 in human cancers, we performed a pan-cancer analysis and examined its topology, localization, and protein interaction network." (PMID 37777564, 2023). "The immune infiltration analysis revealed that EIF4A3 expression was negatively associated with CD8+ and CD4+ T cells and positively with myeloid-derived suppressor cells, macrophage M2, cancer-associated fibroblasts, and Treg cells." (PMID 37180585, 2023). "Next, our pan-cancer analysis found that the expression level of EIF4A3 is significantly higher in most cancers." (PMID 37777564, 2023). "Previous researches have demonstrated that EIF4A3 is recruited by long non-coding RNAs (lncRNAs) or circRNAs in various cancers." (PMID 37940881, 2023). "EIF4A3-induced circCABIN1 directly transmits the resistance phenotype to recipient GBM cells through exosomes by reprogramming the cancer stemness signature." (PMID 36755314, 2023). "EIF4A3 is implicated in GBM, hepatocellular carcinoma, and pancreatic cancer, among other cancer types." (PMID 37294214, 2023). "EIF4A3 is shown to promote the biogenesis of several circRNAs that regulate tumorigenesis in different cancers." (PMID 36932454, 2023). "As previously found that Eif4a3 knockdown induces apoptosis in cancer cells, allosteric inhibitors have been investigated as a potential NMD suppression tool." (PMID 36142288, 2022). "This is consistent with that found in other pathologies, suggesting a crucial role of EIF4A3 dysregulations in cancer development and/or progression." (PMID 36419260, 2022).